SPRN (shadow of prion protein)
Description:
Prion-like protein that has PrP(C)-like neuroprotective activity. May act as a modulator for the biological actions of normal and abnormal PrP (By similarity).
Synonyms: SHO; Shadoo; bA108K14.1; FLJ41197
Tractability: Antibody: its Gene Ontology location is reachable by antibodies, with high confidence; UniProt places it where antibodies can reach, with medium confidence; UniProt predicts a signal peptide or a membrane-spanning region.
Gene: Protein-coding gene on chromosome 10 (133,420,666 to 133,424,625, reverse strand). Ensembl gene ENSG00000203772.
Subcellular location: Cell membrane
Pathways (Reactome):
Metabolism of proteins: Post-translational modification: synthesis of GPI-anchored proteins
Gene Ontology:
Molecular function: nucleic acid binding
Biological process: protein import into nucleus
Cellular component: extracellular region; nucleus; plasma membrane; cytosol; membrane; nucleolus; vesicle
Genetic constraint (gnomAD): Missense variants: 70 observed, 36.68 expected, observed/expected ratio (o/e) 1.91, 90% interval 1.53 to 1.98. Synonymous variants: 37 observed, 21.69 expected, observed/expected ratio (o/e) 1.71, 90% interval 1.29 to 1.96.
Homologues: Orthologues: chimpanzee sprn (99% identical), pig SPRN (85% identical), dog SPRN (81% identical), mouse Sprn (79% identical), rat Sprn (77% identical), guinea pig SPRN (72% identical).
Diseases named in the same sentence as SPRN in open-access papers:
SPRN is named in the same sentence as 15 diseases in open-access papers, as found by Europe PMC text mining. Sharing a sentence is not in itself a finding about the gene and the disease. The quoted sentences say what the papers report.
prion disease (14 papers, 2008 to 2024). A transmissible disease that is caused by a protein that is able to induce abnormal folding of normal cellular proteins, leading to characteristic spongiform brain changes, which are associated with neuronal loss without an inflammatory response. "In contrast, a prion disease-resistant species, horses and chickens have one polymorphism of the SPRN gene." (PMID 38812560, 2024). "The vulnerability of prion diseases in various species is associated with genetic variations in SPRN, as suggested by these studies." (PMID 39272266, 2024). "To identify differences in the number of SNPs between pheasants and other species, we collected polymorphisms in the ORF of the SPRN gene from prion disease-susceptible (human, cattle, goat, sheep) and prion disease-resistant (horse, dog, chicken) species." (PMID 38812560, 2024). "The shadow of prion protein (Sho) encoded by the shadow of prion protein gene (SPRN) is involved in prion disease progress." (PMID 38891635, 2024). "Further research is necessary to explore the SPRN gene in other species and to investigate the relationship between the number of SPRN gene polymorphisms and susceptibility to prion diseases." (PMID 38812560, 2024). "Previous studies have reported that prion disease-susceptible species, including cattle, goats, and sheep, have highly polymorphic SPRN genes." (PMID 38812560, 2024). "The shadow of prion protein (Sho) encoded by the shadow of prion protein gene (SPRN) has been implicated in prion disease biology." (PMID 38891635, 2024). "The SPRN polymorphisms, which contribute to expression level or protein function, show strong associations with the pathogenesis of prion diseases in different species." (PMID 38812560, 2024). "Previous studies have also indicated that genetic characteristics of the SPRN gene are significantly different between prion disease-susceptible species (cattle, goats) and -resistant species (horses, dogs, and chickens)." (PMID 38812560, 2024). "Prion diseases are rare and fatal neurodegenerative disorders associated with the shadow of the prion protein (SPRN) gene." (PMID 39765621, 2024). "SPRN gene in/del polymorphisms have been linked to prion disease susceptibility in animals, including cattle, sheep, and goats." (PMID 39272266, 2024). "In this study, we amplified the SPRN gene sequence by polymerase chain reaction (PCR) and performed multiple sequence alignment of pheasant SPRN gene and Sho protein sequences with those of prion disease-susceptible and -resistant species." (PMID 38812560, 2024). "Future studies should investigate the association of in/del variants with SPRN in prion disease-resistant animals." (PMID 39272266, 2024). "The interaction between Sho and PrP accelerates the PrPSc conversion rate while the SPRN gene polymorphisms have been associated with prion disease susceptibility in several species." (PMID 38891635, 2024). "Recent studies have reported that the shadow of prion protein (Sho) encoded by the shadow of prion protein gene (SPRN) interacts with prion protein (PrP) and accelerates prion diseases." (PMID 35632724, 2022). "Among these cofactors, the shadow of prion protein (Sho) encoded by the shadow of prion protein gene (SPRN) plays a pivotal role in pathogenesis in several types of prion diseases." (PMID 35632724, 2022). "Since the Sho is an important interaction partner for PrP, genetic polymorphisms in the SPRN gene that affect conformational changes and/or the expression level of the Sho protein are related to susceptibility to prion diseases in several hosts." (PMID 35632724, 2022). "Since Sho is involved in the pathological process of PrPSc, genetic polymorphisms of the shadow of the prion protein gene (SPRN) are related to susceptibility to prion diseases in various hosts." (PMID 35782543, 2022).
prion disease (continued). "We compared the distributions of the genetic polymorphisms found in the ORF of the SPRN gene in prion disease-susceptible (human, cattle, goat, and sheep) and prion disease-resistant (horse and dogs) animals." (PMID 35982928, 2022). "SPRN encodes the shadow of prion protein, associated with neurodegenerative human prion diseases including Creutzfeldt–Jakob disease, while knockdown of STK35 in endothelial cells alleviates their migratory ability." (PMID 35328807, 2022). "We searched the polymorphisms found in the ORF of the SPRN gene in prion disease-resistant animals (horse) and prion disease-susceptible animals (human, cattle, goat and sheep) to look for a difference in the number of SNPs between these two groups." (PMID 34573540, 2021). "Prion disease-susceptible animals had polymorphisms that cause amino acid changes in the OFR of the SPRN gene." (PMID 34573540, 2021). "Lastly, we compared the number of SPRN polymorphisms in prion disease-resistant species (horses) and prion disease-susceptible species (humans, cattle, goats and sheep)." (PMID 34573540, 2021). "A previous study has been reported a total of four polymorphisms of the SPRN gene in a prion disease-resistant animal, the horse." (PMID 34573540, 2021). "Although the association of prion diseases with polymorphisms in the SPRN gene has apparently existed, genetic studies of the SPRN gene in Korean cattle, including Hanwoo and Holstein cattle, have not been performed thus far." (PMID 32943703, 2020). "The shadow of prion protein gene (SPRN), a member of the prion gene family, is a potential candidate that is associated with prion disease susceptibility." (PMID 31649311, 2019). "A genetic screen was carried out of the open reading frame of SPRN by direct sequencing in 522 patients with prion disease, including 107 with variant Creutzfeldt–Jakob disease (vCJD), and 861 healthy controls." (PMID 18805828, 2008). "In addition, previous studies have indicated that SPRN polymorphisms are linked to susceptibility to prion diseases, including CJD, scrapie, and BSE." (PMID 39765621, 2024). "The SPRN gene is essential in influencing susceptibility to prion diseases." (PMID 39765621, 2024). "Here, we identified the SPRN gene sequence by polymerase chain reaction (PCR) and compared the SPRN gene and Sho protein sequences among various prion disease-susceptible and -resistant species to identify the distinctive genetic features of pheasant Sho using Clustal Omega." (PMID 38812560, 2024). "In addition, polymorphisms of the SPRN gene in prion disease-susceptible species play a crucial role in determining their susceptibility to prion diseases." (PMID 38812560, 2024). "Thus, in the current study, we examined the genetic polymorphisms of the SPRN gene in raccoon dogs, which are potentially resistant to prion diseases." (PMID 39765621, 2024). "Notably, we found an abundance of single nucleotide polymorphisms in the open reading frame of duck SPRN gene, which is comparable to those in prion disease-susceptible species." (PMID 38891635, 2024). "Exploring the SPRN gene in quails in the context of prion diseases could yield valuable insights into the susceptibility of quails to these diseases and potentially shed light on mechanisms of prion transmission across species." (PMID 39272266, 2024). "We collected reported genetic polymorphisms in the ORF of the SPRN gene in prion disease-susceptible animals (humans, cattle, sheep, goats), and prion disease-resistant animals (dogs, horses, chickens, and ducks (this study) to compare the distribution of SNPs between these two groups." (PMID 38891635, 2024). "Dogs, a prion disease-resistant animal, have one insertion/deletion polymorphism in SPRN gene." (PMID 38812560, 2024). "Notably, the prion disease-susceptible species exhibited several genetic polymorphisms that lead to amino acid changes in the ORF of the SPRN gene." (PMID 38812560, 2024).
prion disease (continued). "Notably, prion disease-susceptible animals had several genetic polymorphisms that cause amino acid changes in the ORF of the SPRN gene." (PMID 35782543, 2022). "In addition, genetic polymorphisms in the SPRN gene are related to susceptibility to prion diseases." (PMID 35632724, 2022). "We collected the polymorphisms found in the ORF of the SPRN gene in prion disease-resistant (horse, chickens) and prion disease-susceptible animals (human, cattle, goat and sheep) to find a difference in the distribution of genetic polymorphisms between these two groups." (PMID 35782543, 2022). "Finally, we compared the number of SPRN polymorphisms between prion disease-resistant species (horses, chickens) and prion disease-susceptible species (humans, cattle, goats and sheep)." (PMID 35782543, 2022). "Finally, we compared the number of SPRN polymorphisms between prion disease-resistant and prion disease-susceptible animals." (PMID 35782543, 2022). "Thus, previous studies have reported that genetic polymorphisms of the SPRN gene that affect the expression level, function, and structure of Sho are involved in susceptibility to several types of prion diseases." (PMID 35982928, 2022). "However, only one genetic polymorphism of the SPRN gene was observed in prion disease-resistant animals, including 423 horses and 201 dogs." (PMID 35982928, 2022). "In addition, genetic polymorphisms of the shadow of the prion protein gene (SPRN) are related to the vulnerability of prion diseases in various hosts." (PMID 35782543, 2022). "Since the expression level of the SPRN gene is important to the pathomechanism of prion diseases, further association analysis using FSE-infected animals and a reporter assay according to the genotype of c.469C > T is highly desirable in the future to validate the effect of c.469C > T." (PMID 35632724, 2022). "Notably, prion disease-susceptible animals, including 904 cattle, 637 goats and 981 sheep showed over seven genetic polymorphisms of the SPRN gene (cattle: 7; goats: 7; sheep: 8)." (PMID 35982928, 2022). "Finally, we compared the SNPs in the coding sequence (CDS) of the SPRN gene between horses and prion disease-susceptible species." (PMID 34573540, 2021). "Therefore, further analysis of the effects, according to synonymous SNPs of the equine SPRN gene on the translation of this gene and the susceptibility to prion diseases in several horse breeds, are needed in the future." (PMID 34573540, 2021). "Thus, a case-control study in sample size-matched large groups to verify the association of the SPRN gene with susceptibility to prion diseases is highly desirable in the future." (PMID 31649311, 2019). "Since these genetic characteristics in prion disease-resistant species were apparently different from the strong LD observed in prion disease-susceptible species, we investigated another prion protein family gene, the SPRN gene, in the horse." (PMID 31905681, 2019). "In previous studies, the shadow of prion protein (Sho) has contributed to an acceleration of conversion from normal prion protein (PrPC) to PrPSc, and the shadow of prion protein gene (SPRN) polymorphisms have been significantly associated with the susceptibility of prion diseases." (PMID 31905681, 2019). "Although confirmation of our findings in further non-UK cases of vCJD and sCJD would be extremely valuable, our data support the hypothesis that SPRN genetic variants are involved in the pathobiology of prion disease." (PMID 18805828, 2008). "Furthermore, genetic variations of the SPRN gene influence susceptibility to prion disease." (PMID 34573540, 2021). "Conversely, SPRN, the most recently identified member of the prion gene family, encoding for a protein (Sho) that is highly conserved among many species, from fish to mammals, may be functionally related to the development of prion diseases." (PMID 23071594, 2012).
prion disease (continued). "The presence of the shadow of prion protein (Sho) produced by the shadow of prion protein gene (SPRN) has been correlated with prion disease." (PMID 39272266, 2024). "The SPRN gene is one of the key factors in prion disease biology through its role in promoting the conversion from PrPC to PrPSc." (PMID 38891635, 2024). "One of the candidate genes involved in prion diseases is the shadow of the prion protein (SPRN) gene." (PMID 39765621, 2024). "Horses, being resistant to prion diseases, exhibit limited genetic association between the PRNP and SPRN genes in comparison to animals susceptible to prion diseases." (PMID 39272266, 2024). "We noticed that various SNPs were found in the ORF of the prion disease-susceptible group, whereas, in the prion disease-resistant group, except for ducks, only one SNP was found in the ORF of the SPRN gene." (PMID 38891635, 2024). "It is clear that genes other than PRNP, such as the SPRN gene, play a role in prion disease progress." (PMID 38891635, 2024). "Nonetheless, Pekin ducks, which have been considered a prion disease-resistant species, display a variety of polymorphisms in the ORF of the SPRN gene." (PMID 38891635, 2024). "Since the Sho protein encoded by the shadow of the prion protein gene (SPRN) plays an essential role in the progression of prion diseases, we investigated the genetic characteristics of the equine SPRN gene in horses." (PMID 34573540, 2021). "Regarding differences in prion disease-related gene sequence among domestic species, cloning of the bovine and ovine SPRN gene revealed a high level of homology." (PMID 23071594, 2012). "Future works are required to address this limitation and further evaluate the features identified in the duck SPRN gene and the duck PRNP gene, which might be present in prion disease-susceptible species." (PMID 38891635, 2024). "To clarify whether prion disease resistance is an unusual characteristic of dogs or a general feature of a Canidae family, we have investigated the SPRN gene in raccoon dogs." (PMID 39765621, 2024). "Until now, genetic polymorphisms of the SPRN gene and the protein structure of Sho related to fragility to prion disease have not been investigated in pheasants, which are a species of poultry." (PMID 38812560, 2024). "The absence of genetic polymorphisms in the ORF of the SPRN gene, which affects protein structure and expression level, seems to be a unique characteristic of prion disease-resistant animals, including horses and chickens." (PMID 35782543, 2022). "Since genetic variations of the SPRN gene may affect the vulnerability to prion disease via structural changes and the expression level of proteins, we investigated the genetic characteristics of the equine SPRN gene." (PMID 34573540, 2021). "Since several non-synonymous SNPs of the SPRN gene were reported in prion diseases-susceptible animals, the absence of non-synonymous SNP of the SPRN gene in the horses is noticeable." (PMID 34573540, 2021). "Since several non-synonymous SNPs of the SPRN gene have been reported in prion diseases-susceptible animals, the absence of non-synonymous SNP of the equine SPRN gene in the horses is noticeable." (PMID 34573540, 2021). "Although several case-control studies in various hosts of prion disease have reported associations between SPRN polymorphisms and prion disease susceptibilities, polymorphisms of the SPRN gene in Korean native goats have not been reported thus far." (PMID 31649311, 2019). "Since previous studies have reported that in/del polymorphisms of the SPRN gene were associated with the susceptibility of prion disease in cattle, sheep, and humans, no in/del polymorphism of the equine SPRN gene is noteworthy." (PMID 31905681, 2019). "We found a total of four polymorphisms in the equine SPRN gene; however, we did not observe an in/del polymorphism, which is correlated with the susceptibility of prion disease in prion disease-susceptible animals." (PMID 31905681, 2019).
prion disease (continued). "Further studies on SPRN gene or its protein Sho could strengthen our understanding regarding prion disease and may provide useful in deciphering several unresolved facets of prion biology." (PMID 23071594, 2012). "However, studies on the genetic properties of the SPRN gene in quails linked to prion diseases have not been conducted." (PMID 39272266, 2024). "However, to date, polymorphisms and genetic features of the SPRN gene have not been investigated in chickens, which are prion disease-resistant animals." (PMID 35782543, 2022). "This indicates that the SPRN gene may be another potent candidate gene associated with the susceptibility to prion diseases regardless of the genotype of the PRNP gene." (PMID 31649311, 2019). "Interestingly, all SPRN SNPs showed weak LD with PRNP SNPs in horses and pheasants, both prion disease-resistant animals." (PMID 39765621, 2024). "Although the PRNP and PRND genes have been studied in prion disease-resistant species, a member of the prion gene family called the shadow of prion protein gene (SPRN) has not been reported thus far in horses." (PMID 31905681, 2019). "Furthermore, we investigated LD between SPRN and PRNP SNPs because the LD value among prion family genes has showed distinct features in prion disease-resistant animals." (PMID 31905681, 2019).